ACTA2-AS1 (ACTA2 antisense RNA 1)
Synonyms: uc001kfo.1; ZXF1; UC001kfo
Gene: Long non-coding RNA gene on chromosome 10 (88,932,390 to 88,940,820, forward strand). Ensembl gene ENSG00000180139.
Diseases named in the same sentence as ACTA2-AS1 in open-access papers:
ACTA2-AS1 is named in the same sentence as 6 diseases in open-access papers, as found by Europe PMC text mining. Sharing a sentence is not in itself a finding about the gene and the disease.
ACTA2-AS1 shares sentences with these, for which no sentence is quoted: cancer (2 papers); tumor (2); endometrial carcinoma (1); endometrioid endometrial carcinoma (1); lung adenocarcinoma (1); lung carcinoma (1).